MIR210 (microRNA 210)
Synonyms: hsa-mir-210; MIRN210; mir-210
Gene: MicroRNA gene on chromosome 11 (568,089 to 568,198, reverse strand). Ensembl gene ENSG00000199038.
Gene Ontology:
Biological process: miRNA-mediated post-transcriptional gene silencing
Cellular component: RISC complex
Diseases named in the same sentence as MIR210 in open-access papers:
MIR210 is named in the same sentence as 1 disease in open-access papers, as found by Europe PMC text mining. Sharing a sentence is not in itself a finding about the gene and the disease. The quoted sentences say what the papers report.
tumor (3 papers, 2022 to 2023). "It has been known for some time that, for example, Mir210 is induced by hypoxia and that this can lead to changes in gene expression and tumor cell function." (PMID 38069241, 2023).